RN7SKP121 (RN7SK pseudogene 121)
Gene: Miscellaneous RNA gene on chromosome 11 (127,406,028 to 127,406,332, reverse strand). Ensembl gene ENSG00000222774.
Homologues: Orthologues: chimpanzee 7SK (99% identical), guinea pig 7SK (63% identical). Paralogues in human: RN7SKP176 (74% identical), RN7SKP79 (73% identical), RN7SKP20 (72% identical), RN7SKP9 (72% identical), RN7SKP37 (72% identical), RN7SKP77 (72% identical), 7SK (70% identical), RN7SKP189 (70% identical), RN7SKP217 (70% identical), RN7SKP90 (70% identical), RN7SKP243 (70% identical), RN7SKP250 (70% identical), and 284 more.